LEP (leptin)
Diseases named in the same sentence as LEP in open-access papers (continued):
Sharing a sentence is not in itself a finding about the gene and the disease.
atherosclerosis (continued). "Adipose tissue-derived factors, known as adipokines (such as adiponectin, leptin, resistin, retinol-binding protein 4 (RBP-4) and visfatin), influence atherosclerosis development and can have either protective or aggravating effects." (PMID 37512134, 2023). "Adipokines from adipose tissue, such as resistin, leptin, adiponectin, and TNF, play a vital role in the inflammation process, which is the main reason for the development of atherosclerosis." (PMID 36299943, 2022). "Overall, a collection of in vivo and in vitro results, including recent data from our laboratory, emphasize a regulatory role of leptin in VSMC activation and phenotypic transformation, central to the pathogenesis of atherosclerosis." (PMID 34064112, 2021). "The association between subclinical atherosclerosis and two adipokines of opposing effects, adiponectin, and leptin, was examined by measuring coronary artery calcification (CAC) as a determinant of subclinical atherosclerosis." (PMID 34836382, 2021). "The maximum expression of the LEP in the PVAT was observed much later and in patients with an extremely severe degree of CA atherosclerosis." (PMID 33735200, 2021). "In addition, exogenous leptin influences IL1B and TNFA gene expressions, which may moderate the inflammatory reaction progress in this examined adipose tissue, showing leptin as a significant risk factor in atherosclerosis progression." (PMID 31780867, 2019). "The significant higher level of IL-6, TSH and Leptin in serum in the subjects with PD ≥4 mm further support the notion that, in obese subjects, periodontal disease is part of an systemic inflammation that might, in the long run, lead to atherosclerosis and CVD." (PMID 25884594, 2015). "Hypoxia in HCASMCs increases leptin expression through the induction of AngII, ROS, and the JNK pathway to enhance atherosclerosis in HCASMCs." (PMID 25573199, 2015). "Some studies have addressed the possible role of EAT in coronary atherosclerosis, such as an increase of local EAT leptin, and inflammatory cytokine secretion, or a decrease of adiponectin production, which might directly be diffused into adjacent coronary circulation and influence atherosclerosis." (PMID 25383099, 2014). "Moreover, it has been proposed that leptin plays a pathogenic role in atheromatous plaques, due to its positive association with C-reactive protein (CRP) and soluble IL-6 receptor (sIL-6R), two inflammatory mediators involved in the pathogenesis of atherosclerosis." (PMID 22910888, 2012). "In multiple linear regression, cIMT (a subclinical atherosclerosis marker) positively correlated with CRT exposure (p = 0.029), diastolic BP (p = 0.016), and leptin-to-adiponectin ratio (p = 0.048), confirming CRT’s impact on fat distribution and potential role in atherosclerosis." (PMID 41228239, 2025). "Since high molecular weight adiponectin, leptin and RBP-4 did not have statistically significant associations with subclinical atherosclerosis, they were not included in the further analysis." (PMID 37512134, 2023). "UA showed an efficient activity against in vitro leptin-induced atherosclerosis in rat vascular smooth muscle cells; in terms of molecular mechanism, UA exhibited an inhibitory effect on ERK1/2 activation, NF-kB expression, and leptin-induced MMP2 activity, hence decreasing ROS production." (PMID 35887090, 2022). "This literature review aims to outline the steps by which leptin leads to CAD and atherosclerosis." (PMID 34178553, 2021). "A growing body of literature supports the growth-promoting effects of leptin on VSMC that may likely attribute to leptin-induced neointimal growth, vessel remodeling and atherosclerosis." (PMID 34064112, 2021). "We should not rule out the direct action of leptin on such phenomena as atherosclerosis, endothelial dysfunction, and thrombosis." (PMID 32121175, 2020).
atherosclerosis (continued). "Adipokines released by PVAT include adiponectin, leptin, resistin, visfatin, chemerin, lipocalin-2 (LCN2), fatty acid binding protein (FABP), which show direct evidence of PVAT-derived adipokines have effects on the progression of atherosclerosis." (PMID 30305178, 2018). "First, we compared atherosclerosis in the aortic arch of age-matched (24 weeks) C57BL/6J control (n = 10), LDL-receptor deficient (n = 8), leptin-deficient ob/ob (n = 10), and double knock-out (lacking LDL-receptor and leptin) mice (n = 12)." (PMID 28122051, 2017). "Per os administration of colchicine did not influence atherosclerosis progression in cholesterol-fed rabbits, levels of IL-18, insulin and leptin." (PMID 28950870, 2017). "Colchicine did not have a deterrent effect on the development of atherosclerosis either directly or indirectly by regulating the levels of leptin." (PMID 28950870, 2017). "Leptin also stimulates the secretion of inflammatory markers such as CRP, TNF-α and IL-6, which are directly involved in the development of endothelial dysfunction and atherosclerosis." (PMID 27598978, 2017). "Lastly, we did not evaluate adipocytokines, such as leptin, adiponectin, resistin, chemerin and visfatin, knowing their relationship with atherosclerosis and angiogenesis." (PMID 26895298, 2016). "Leptin, produced mainly by white adipose tissue, is a hormone that promotes vascular smooth muscle cell (VSMC) migration and proliferation, a process involved in the pathophysiology of atherosclerosis." (PMID 25573199, 2015). "The direct action of leptin on the vascular wall is supported by an experimental study which found that ob/ob mice, which lack leptin, became hyperphagic and obese but did not develop atherosclerosis." (PMID 34202323, 2021). "On the other hand, it is not clear whether increased leptin or leptin resistance is the mediator of atherosclerosis, and clinical prospective studies are needed to further clarify the role of leptin in cardiovascular disease." (PMID 32824322, 2020). "Moreover, it is known that leptin can regulate cholesterol ester (CE) metabolism by activating the Hormone-sensitive Lipase (HSL) in macrophages, an enzyme that carries out the breakdown of CE, therefore protecting against atherosclerosis." (PMID 30642114, 2019). "Thus, having a dysregulated adiponectin and leptin profile, as showed in GDM women, may potentially have deleterious effects on atherosclerosis development." (PMID 28068986, 2017). "Adipocytokines such as leptin, adiponectin, resistin, interleukin-6 (IL-6) and tumor necrosis factor-α (TNF-α) are mediators produced by adipocytes which have important roles in the pathophysiology of insulin resistance, inflammation, hypertension, endothelial dysfunction and atherosclerosis." (PMID 28747175, 2017). "Concerning the role of leptin in atherosclerosis, we did not deduce a clear role of it." (PMID 28950870, 2017). "Indeed, in a recent investigation by Hahn and colleagues, twice weekly intraperitoneally administered leptin increased proinflammatory high density lipoprotein scores and atherosclerosis in high fat diet fed lupus prone mice but not in nonautoimmune controls." (PMID 23690663, 2013). "Serum leptin level may be a predictor of the left ventricular ejection fraction and the degree of atherosclerosis but not of coronary reperfusion." (PMID 22642879, 2012). "EAT secretes various proinflammatory adipokines like interleukin (IL)-1, IL-6, IL-8, IL-10, tumor necrose factor (TNF) α, leptin, macrophage chemoattractand protein 1 (MCP-1), type I plasminogen activator inhibitor (PAI-1), resistin that provide a metabolic milieu that promotes atherosclerosis." (PMID 23133630, 2012). "Notably, these correlations might suggest a link between the metabolome and protein markers related to immune signalling (LTα, CD6, CCL21, SELE), energy balance and metabolism-related hormones (IGFBP1, SHGB, ADM, leptin, and STC1), and atherosclerosis/thrombosis inhibitor (PAI1)." (PMID 39154540, 2024).
atherosclerosis (continued). "However, it does not directly prove that leptin could attenuate atherosclerosis, in nondiabetics per se." (PMID 26064110, 2015).
depression (229 papers, 2007 to 2026). "Leptin is involved in immunometabolic regulation and energy balance, acting as a pro-inflammatory adipokine linked to depression severity." (PMID 41584756, 2025). "This has been attributed to depression-linked increases in cortisol levels resulting in increased stimulation of leptin secretion." (PMID 38674096, 2024). "Leptin play an important role in the signaling pathway of glutamatergic neurons for regulating depression-related behaviors, suggesting a possible association between synaptic depression and behavioral manifestations of depression." (PMID 38654347, 2024). "Primary obesity is characterized by leptin resistance which is considered a possible risk phenotype for depression." (PMID 38523835, 2024). "Preclinical research has evidenced that injection of leptin produced antidepressant activity, suggesting that deficiency of leptin plays a role in depression." (PMID 38287453, 2024). "Many studies discuss multiple common pathological mechanisms involved in obesity and depression like chronic systemic inflammation, the dopaminergic reward system, vitamin D deficiency and neuroendocrine mechanisms via leptin melanocortinergic—BDNF signaling." (PMID 38523835, 2024). "Some studies have shown that elevated leptin concentrations and leptin resistance are linked to depression-related appetite increase or atypical features in MDD." (PMID 38678012, 2024). "Univariate analysis showed that amount of weight loss, older age, higher leptin level, higher physical activity score, and lower depression score were associated with diet intervention completion." (PMID 37599685, 2023). "These pathways, all of which have been implicated in depression, mediate leptin signaling on targets affecting neurotransmitter regulation, antidepressant activity, neuronal spine density, and glucocorticoid resistance." (PMID 37443383, 2023). "Clinical research revealed that elevated serum leptin levels in young people with major depression were linked with the degree of depression." (PMID 37399205, 2023). "On the other hand, chronically elevated levels of leptin can cause N-methyl-D-aspartate (NMDA) receptor-mediated depression." (PMID 37233709, 2023). "In sum, research indicates that insulin, leptin, and adiponectin are linked to inflammation, reward signaling, and depression, but it is still unclear how these hormones relate to altered brain reward processing in MDD as a function of inflammation." (PMID 37443383, 2023). "Recent studies suggested an association between leptin dysregulation and depression, possibly through brain neurogenesis pathways." (PMID 38098007, 2023). "Is there a role for leptin in the reduction of depression symptoms during weight loss therapy in obese adolescent girls and boys?" (PMID 35195206, 2022). "The associations among depression, unhealthy lifestyle factors (e.g., chronic stress conditions and unhealthy dietary habits), and leptin are complex." (PMID 35911226, 2022). "Being underweight is partly caused by poor nutrition; therefore, low levels of leptin, a mood change-related mediator, have been implicated in the depression development." (PMID 36354390, 2022). "In 25 of 27 cases associations between ghrelin, leptin and adiponectin levels and depression scale sub-scores reflecting changes of weight or appetite and sleep disturbances failed to be statistically significant." (PMID 35633817, 2022). "With regard to biological factors, for women, lower cholesterol levels were associated with depression and higher leptin levels with depressed mood." (PMID 33614574, 2021). "Studies on the association between adiponectin and leptin and anxiety and depression among postmenopausal women are limited." (PMID 33667284, 2021). "Leptin levels measured at discharge were associated with increased incidence of post-stroke depression in the following month." (PMID 34445740, 2021).
depression (continued). "Clinical studies on the possible association of leptin levels with anxiety and depression are relatively limited and divergent." (PMID 33667284, 2021). "In conclusion, our findings show that depression and anxiety symptoms are significantly associated with circulating adiponectin and leptin levels in postmenopausal women." (PMID 33667284, 2021). "The data show that adiponectin and leptin levels are significantly associated with depression and anxiety symptoms." (PMID 33667284, 2021). "For men, higher interleukin-6 levels and higher hs-CRP levels were associated with depression and social isolation, higher leptin levels predicted depression and social isolation." (PMID 33614574, 2021). "Endocrine molecules, especially leptin and adiponectin, are known to be associated with depression by regulating the hypothalamic-pituitary-adrenal (HPA) axis and neuronal plasticity in the brain." (PMID 34955919, 2021). "To begin, authors claiming that depression are associated with low leptin levels, thus suggesting a positive association/correlation between leptin levels and improvement in the depressive mood." (PMID 32033608, 2020). "Findings in mediation models implicate a causal role for elevated leptin levels in the pathophysiology of depression." (PMID 32699219, 2020). "Some authors stated that depression is associated with low circulating and brain leptin levels, suggesting a correlation between leptin levels and the depressive mood." (PMID 33066277, 2020). "There is evidence that increased hypothalamus levels of leptin facilitate a cognition and synaptic plasticity, but leptin resistance, in contrast, increases the risk of depression in patients with AO and T2DM." (PMID 33240938, 2020). "Taken together, all these data indicate the necessity of further investigation about circulating leptin levels in depressive disorders to understand its real impact on cardiovascular risk and thrombosis." (PMID 33066277, 2020). "Low levels of leptin are associated to depression in humans, and preclinical models as well as pharmacological studies indicate leptin as a potential antidepressant drug." (PMID 30804991, 2019). "There is also evidence to support the association between atypical features of depression, such as increase appetite and hyposomnia with elevated leptin levels." (PMID 30405455, 2018). "Antibiotic use, which has been found as a risk factor for the development of depression has also been shown to reduce leptin levels in rodents." (PMID 30405455, 2018). "In fact, the hyperleptinemia that has been observed in some cases of depression seems to associated more with central leptin resistance induced by adiposity and metabolic abnormities characterized by impaired leptin sensitivity." (PMID 30367065, 2018). "A further marked feature of depression is that it appears to be associated with altered leptin homeostasis." (PMID 29190710, 2017). "In HSS patients, higher leptin levels were associated with greater feelings of depression, anxiety, and stress whereas in LSS patients a higher leptin level showed the trend to be associated with lower psychological symptom burden." (PMID 28030575, 2016). "IGF-1 has been described as a potential biomarker for mood disorders and leptin has also been implicated in anxiety and depression related responses; thus, it is possible that leptin and IGF-1 interact in the regulation of central nervous system functions." (PMID 26382238, 2015). "Low leptin levels have been found to be associated with human depression and depression-like behaviors in rodents." (PMID 25225489, 2014). "We found that patients with high leptin levels have a higher risk of developing major depression 3 months after stroke, even after adjustments for others risk factors." (PMID 25061971, 2014). "Consistent with our results, a recently published study including 104 patients with stroke showed that leptin was a powerful biological marker of risk of developing depression 1 month after stroke." (PMID 25061971, 2014).